SMAD3 (SMAD family member 3)
Diseases named in the same sentence as SMAD3 in open-access papers (continued):
Sharing a sentence is not in itself a finding about the gene and the disease.
gastric cancer (65 papers, 2010 to 2026). A primary or metastatic malignant neoplasm involving the stomach. "Smad3-/- mice exhibit metastatic colon cancer and the loss of Smad3 expression increases susceptibility to tumorigenicity in human gastric cancer." (PMID 38543494, 2024). "Conversely, increased SMAD3 expression was associated with shorter overall survival in esophageal squamous cell carcinoma and gastric cancer." (PMID 35681731, 2022). "Analysis showed that high expression levels of SMAD1, SMAD2, and SMAD4 are associated with a better survival rate of gastric cancer patients, whereas SMAD3, SMAD5, SMAD6, SMAD7 and SMAD9 are associated with poor prognosis." (PMID 34138687, 2021). "In fact, meta-analysis of published microarray datasets revealed that increased TMEPAI and Smad3 expression and decreased Smad2 expression in lung and gastric cancers was significantly associated with poorer patient prognosis." (PMID 31798766, 2019). "Further supporting the tumor suppressor role of SMAD3, its downregulation has been associated with acute T‐cell lymphoblastic leukemia, as well as gastric cancer." (PMID 29130642, 2018). "Deficient SMAD3 expression is related to human gastric cancer." (PMID 33036415, 2020). "Similarly, when Smad3 is introduced into SNU-484 human gastric cancer cells (Smad3 deficient), they recover TGFβ sensitivity, reduced tumorigenicity and enhanced expression of the tumor suppressor E-cadherin." (PMID 22204491, 2011). "Melatonin inhibits the proliferation of gastric cancer cells through regulating the miR-16-5p-Smad3 pathway, hat circadian rhythms are involved in treating gastric cancer by regulating the miR-16-5p-Smad3 pathway." (PMID 39062777, 2024). "Low levels of Smad3 expression are observed in human breast and gastric cancers, and this decreased expression can change the effects of Smad3 from tumor suppressing to tumor promoting." (PMID 38569937, 2024). "Further studies have revealed that overexpression of GCNT4 can prevent the growth of gastric cancer cells by regulating the TGF-β1/SMAD3 pathway." (PMID 36158645, 2022). "In PTCH1mut cells, dysregulated Hh signalling is associated with the upregulation of SMAD2, 3, and 4 mRNA, as was also shown for SMAD3 in gastric cancers." (PMID 35159339, 2022). "Li and his colleagues demonstrated that IGHG1 promotes the proliferation, migration and invasion of gastric cancer cells through regulation of TGF-β/SMAD3 signaling pathway." (PMID 35167648, 2022). "The loss of embryonic liver cell lining protein (ELF) can destroy the TGF-mediated signal pathway by interfering with the localization of Smad3 and Smad4 and lead to gastric cancer." (PMID 35847949, 2022). "Melatonin exposure significantly attenuated gastric cancer by enhancing miR-16-5p expression which targeted SMAD3 and resulted in negative regulation of its abundance." (PMID 35668933, 2022). "Over-expression of miR-424-5p promoted cell proliferation and inhibited Smad3 expression through the TGF-beta pathway in gastric cancer." (PMID 35360837, 2022). "Collectively, these results demonstrate that the high expression level of three members of SMADs (SMAD1, SMAD2, and SMAD4) is significantly correlated with favorable OS of gastric cancer patients, which is opposite to SMAD3." (PMID 34138687, 2021). "TGF-β1 inhibitors have been reported to block migration, invasion, and epithelial–mesenchymal transformation of gastric cancer cells and inhibit the phosphorylation of SMAD3." (PMID 34696660, 2021). "Altogether, we proposed that targeting of GCNT4 and activation of the TGF-β1/SMAD3 signaling pathway by miR-130a-3p enhanced the growth of gastric cancer cells." (PMID 34696660, 2021). "The (E)-SIS3 was used to inhibit SMAD3 expression in gastric cancer cells, and the effects of SMAD3 on gastric cancer cells were analyzed via real-time cellular analysis (RTCA), flow cytometry, colony formation, and immunofluorescence assay." (PMID 34138687, 2021).
gastric cancer (continued). "Through in vitro experiments, we further confirmed the effect of SMAD3 on the proliferation, migration and apoptosis of gastric cancer cells AGS and MGC803." (PMID 34138687, 2021). "This indicated that GCNT4 overexpression in gastric cancer cells inhibited the TGF-β1/SMAD3 signaling pathway activated by miR-130a-3p upregulation." (PMID 34696660, 2021). "This study provides important strategies for the selection of therapeutic targets for gastric cancer treatment involving miR-130a-3p/GCNT4/TGF-β1/SMAD3 axis." (PMID 34696660, 2021). "On the other hand, SMAD3, SMAD5, SMAD6, and SMAD7 were associated with poor OS in the second and third stage of gastric cancer." (PMID 34138687, 2021). "A previous study reported that overexpression of SMAD3 decreases inhibition of melatonin in gastric cancer cells." (PMID 34138687, 2021). "In order to further verify the inhibitory effect of (E)-SIS3 on gastric cancer cell SMAD3, we measured the mRNA levels of SMAD3 gene in two gastric cancer cell lines treated with (E)-SIS3." (PMID 34138687, 2021). "Previous studies have shown that TGF-β1/SMAD3 signaling is involved in the progression of gastric cancer." (PMID 34696660, 2021). "Inhibition of SMAD3 inhibited the proliferation of gastric cancer cells, migration and promoted apoptosis." (PMID 34138687, 2021). "High expression level of SMAD3 was correlated with poor OS in moderate and well-differentiated gastric cancer." (PMID 34138687, 2021). "The results showed that the expression of p-Smad2 and p-Smad3 in metastatic gastric cancer cells was obviously higher than those in primary gastric cancer cells." (PMID 32139657, 2020). "Hypomethylated SMAD3 was found in cancers of the digestive system, such as liver cancer (8/12, 66.6%), gastric cancer (1/2, 50%), colon cancer (36/38, 94.7%), and rectal cancer (7/7, 100%)." (PMID 33036415, 2020). "According to the datasets from TCGA, SMAD3 was hypomethylated in cancers of the digestive system, such as liver cancer, gastric cancer, colon cancer, and rectal cancer." (PMID 33036415, 2020). "Promotion of ECAD expression by ectopically expressed SMAD3 was demonstrated before in a gastric cancer cell line." (PMID 33260366, 2020). "SMAD3 induced ECAD in a gastric cancer cell line following transcriptional induction of the miR-200b/a promoter and subsequent inhibition of ZEB1 expression." (PMID 33260366, 2020). "The expressions of p-Smad2 and p-Smad3 in peritoneal mesothelial cells were significantly upregulated in the presence of metastatic gastric cancer cell supernatants." (PMID 32139657, 2020). "MiR-424 which had the largest weight in the up-regulated miRNAs was reported to promote the proliferation of gastric cancer by targeting Smad3 via TGF-u signaling pathway." (PMID 29879180, 2018). "We also found that miR-424-5p promotes proliferation of gastric cancer cells by targeting Smad3 through TGF-β signaling pathways." (PMID 27655675, 2016). "Smad3 was also found to be involved in the transcriptional activation of Bim in human gastric carcinoma cells when simultaneously exposed to both TGFβ and TNFα." (PMID 26405162, 2015). "In gastric cancer, Han found low levels of Smad3 in 3 out of 8 patients and in nine human gastric cancer cell lines." (PMID 22539990, 2012). "Although mutations in SMAD3 have not been reported, 3 out of 8 (37.5%) gastric tumors in one report showed low to undetectable levels of SMAD3 expression and restoration of SMAD3 suppressed tumorigenicity of gastric cancer cells." (PMID 20573232, 2010). "SMAD3 is a key mediator of TGF-β signaling that functions as a tumor suppressor in early gastric carcinogenesis but can promote invasion and metastasis in advanced stages, and its loss is observed in approximately 15%–20% of human gastric cancers." (PMID 40673273, 2025). "Moreover, hsa-miR-424-5p was upregulated in gastric cancer and promoted the proliferation of gastric cancer cells by targeting Smad3 through the TGF-β signaling pathways." (PMID 36142686, 2022).
gastric cancer (continued). "Notably, SMAD3 is activated in gastric cancer cells that are stimulated with Shh and the expression of GLI1 and GLI2 is upregulated by TGF-β/SMADs." (PMID 35159339, 2022). "Treatment with melatonin suppressed gastric cancer via upregulation of miR-16-5p expression and downregulation of SMAD3, indicating that the TGF-β/SMAD pathway might be a possible molecular mechanism by which melatonin precludes cancer progression." (PMID 35668933, 2022). "Besides, a recent study showed that ADAM17 knockdown inhibited the expression of TGF-β in gastric carcinoma cells, with the downstream Smad2 and Smad3 also being attenuated." (PMID 36313337, 2022). "Therefore, it is particularly important to study changes in the TGF-β1/SMAD3 signaling pathway in gastric cancer." (PMID 34696660, 2021). "Moreover, (E)-SIS3 pharmacological assay revealed that inhibition of expression of SMAD3 suppressed the proliferation and migration ability of gastric cancer cells via inducing apoptosis." (PMID 34138687, 2021). "Furthermore, melatonin was shown to suppress the proliferation of gastric cancer cells by promoting the expression of miR-16-5p, which targeted Smad3." (PMID 32982740, 2020). "Melatonin inhibits gastric cancer cell growth via miR-16-5p/Smad3 pathway." (PMID 33344223, 2020). "TGFβ could sensitize gastric carcinoma cells to TNFα-induced apoptosis where TGFβ is responsible for Smad3-induced Bim transcription and TNFα to JNK-mediated stabilization of the Bim protein." (PMID 26405162, 2015). "Low or undetectable level of SMAD3 was observed in 37.5% of human gastric cancer tissues." (PMID 22943793, 2012). "In addition, it was reported that IGHG1 could induce EMT in gastric cancer cells by regulating TGF-β/SMAD3 signaling pathway, which is in line with our study." (PMID 34315496, 2021). "Therefore, we elucidated the role of the miR-130a-3p/GCNT4/TGF-β1/SMAD3 axis in gastric cancer genesis, which could provide potential therapeutic targets for gastric cancer involving both miR-130a-3p and GCNT4." (PMID 34696660, 2021). "There are several signaling pathways involved in gastric cancer development and progression, including Wnt/beta-catenin, Hedgehog, TGF-β/SMAD3, MAPK, and PI3K/AKT/mTOR signaling pathway." (PMID 35167648, 2022). "The findings of this study have important implications for the selection of therapeutic targets for gastric cancer treatment involving miR-130a-3p/GCNT4 and TGF-β1/SMAD3 axes." (PMID 34696660, 2021). "Mechanistically, miR-130a-3p suppressed gastric cancer genesis by inhibiting GCNT4 expression and activating the TGF-β1/SMAD3 signaling pathway." (PMID 34696660, 2021). "MiR-204 inhibits the phosphorylation of SMAD2 and SMAD3 by directly targeting TGF-β receptor 2, which further contributes to the inhibition of EMT and elevates the sensitivity to 5-fluorouracil in gastric cancer cells." (PMID 34686196, 2021). "In gastric cancer cells, TGF-β, via SMAD3, stimulates the expression of the histone demethylase RBP2, which reciprocally augments SMAD3 activity." (PMID 34249916, 2021). "The band proteins intensities displayed that the proteins of p-Akt, p-Smad3, and β-catenin were remarkably downregulated but p-Smad2 was upregulated when added BBR (10, 20, and 40 μM for 24 h) in HepG2 and gastric cancer cells." (PMID 34712379, 2021). "This indicates that miR-130a-3p participates in the regulation of gastric cancer cell behavior by targeting GCNT4 and inducing activation of the TGF-β1/SMAD3 signaling pathway." (PMID 34696660, 2021). "Overall, this study revealed that miR-130a-3p aggravated gastric cancer cell proliferation, migration, and invasion by reducing GCNT4 expression and activating the TGF-β1/SMAD3 signaling pathway." (PMID 34696660, 2021).
gastric cancer (continued). "sFRP1 reinstates glycogen synthase kinase 3β (GSK3β) activity, thereby facilitating Rac1 activation, while ectopic overexpression of Rac1 concurrently suppresses SMAD family member 3 (Smad3) activity; these interactions collectively enhance the malignant phenotype of EMT in gastric cancer." (PMID 41188920, 2025). "However, in gastric cancer cells, Smad3-mediated TGF-β signaling induces carcinoembryonic antigen (CEA)-related cell adhesion molecule 6 (CEACAM6) expression and promotes EMT in gastric cancer cells." (PMID 38818471, 2024). "In gastric cancer (GC), evidence presents that MSCs secreted TGF-β1 promotes fatty acid oxidation (FAO) to support stemness features and drug resistance, which is mediated by activating SMAD2 and SMAD3 and promoting lncRNA MACC1AS1 expression." (PMID 34095111, 2021). "Thus, immunohistochemistry was performed on 98 paraffin embedded gastric cancer specimens, and p‐AMPK, p‐Smad3 and TGF‐β1 levels were examined." (PMID 33538080, 2021). "We hypothesized that miR-130a-3p facilitates gastric cancer progression by downregulating GCNT4, which blocks the activation of the TGF-β1/SMAD3 signaling pathway." (PMID 34696660, 2021). "We hypothesized that miR-130a-3p promotes the progression of gastric cancer by downregulating GCNT4, which blocks the activation of the TGF-β1/SMAD3 signaling pathway." (PMID 34696660, 2021). "The signals of TGF-β1 to transcriptional induction of VEGF-C can be mediated via canonical Smad3 in some gastric cancer cells, while it can also be conveyed via the non-canonical Smad-independent Akt pathway." (PMID 31409309, 2019). "In addition, EMT regulators, such as Snail and Slug, were upregulated in lysates and exosomes derived from DSGOST-treated gastric cancer cells, and TGFβ1 plus DSGOST treatment induced EMT signaling via phosphorylation of Smad2 and Smad3." (PMID 29844404, 2018). "Here, we demonstrated that the histone demethylase RBP2 was crucial for TGF-β1-(p-Smad3)-RBP2-E-cadherin-Smad3 feedback circuit that was implicated in malignant progression of tumors and its knockdown significantly inhibited gastric cancer (GC) metastasis both in vitro and in vivo." (PMID 25974964, 2015). "In addition, we also detected TGFβRI which mediated the phosphorylation of Smad3 and was required for RBP2 upregulation in response to TGF-β1 in gastric cancer specimen." (PMID 25974964, 2015). "Compared with the blank group, the expression of p-Smad3 protein in gastric cancer cells (Hgc27 and MKN45) in the M2c co culture group showed the same trend, while there was a significant difference in Smad3 protein expression between the two gastric cancer cell lines M2c co culture groups." (PMID 39991579, 2025). "METTL3 knockdown significantly inhibited the growth of gastric cancer(GC), and METTL3 acted as a methyltransferase to regulate the expression of genes related to the TGF-β/smad pathway, especially METTL3 modifies Smad3 mRNA through m6A." (PMID 39289775, 2024). "Higher concentrations of N-Shh (human recombinant form of Shh) enhanced cell motility and invasiveness in gastric cancer cells; moreover, treatment of cells with N-Shh led to enhanced TGF-β1 secretion, TGF-β-mediated transcriptional response, expression of ALK5 protein and phosphorylation of SMAD3." (PMID 22943793, 2012). "Besides measuring P-Smad2 in gastric cancer, we used real-time PCR to detect mRNA expression of Smad2 and Smad3 in gastric cancer and surrounding non-tumor tissues from 16 patients." (PMID 22539990, 2012). "According to our results, Smad3 is not directly linked with characteristics of gastric cancer, however, our data indicated that it may play a role in cancer associated fibroblasts and EMT of gastric cancer cells." (PMID 22539990, 2012).
colorectal cancer (63 papers, 2011 to 2026). A primary or metastatic malignant neoplasm that affects the colon or rectum. "Smad3−/− mice are deficient in the transforming growth factor beta (TGFβ) signaling molecule, SMAD3, resulting in dysregulation of the cellular pathway most commonly affected in human colorectal cancer, and develop inflammation-associated colon cancer." (PMID 24244446, 2013). "We have utilized DSS to induce inflammation and cancer without the use of an additional carcinogen, in TGFβ signaling-deficient Smad3−/− mice, which are defective in one of the most common signaling pathways mutated in human colorectal cancer." (PMID 24244446, 2013). "The loss of SMAD3 expression and function is involved in susceptibility to gastric cancers, colorectal cancers and acute T-cell lymphoblastic leukemia." (PMID 21835029, 2011). "Inactivating mutations of Smad2 have been identified in ~6% of colorectal cancers while loss of function mutations of Smad3 are rare in colorectal cancers." (PMID 22204556, 2011). "By contrast, the Smad3 mutation is rare and found mostly in colorectal cancer." (PMID 38569937, 2024). "In this study, we demonstrate that Smad3 is significantly downregulated in MDSC from colorectal cancer (CRC) patients and tumor-bearing mouse models, impairing monocytic lineage maturation." (PMID 41360769, 2025). "High expression of SMAD3 is correlated with poor prognosis, indicating its important role in the progression of colorectal cancer." (PMID 40466864, 2025). "Line with these findings, MDSC from colorectal cancer (CRC) patients displayed lower Smad3 expression than those from healthy donors." (PMID 41360769, 2025). "It has been shown to inhibit the phosphorylation of TGF-β/Smad3 in other cancers, such as colorectal cancer." (PMID 36792585, 2023). "About 40% of colorectal cancer (CRC) patients harbor mutations in the TGF-β signaling pathway, often rendering SMAD3/4 canonical transcription unresponsive." (PMID 35626109, 2022). "Kindlin-1 interacts with transforming/tumor growth factor β (TGF-β)/ SMAD family member 3 (Smad3) signaling components to promote the TGF-β-induced migration in colorectal cancer." (PMID 35096085, 2022). "Smad3 protects against the development of colorectal tumors, and specifically, knockout of exon 2 in Smad3 promotes metastasis of large bowel cancer." (PMID 34966673, 2021). "Apart from competing interacting with SMAD3 in acquired regorafenib-resistance, miR-145 antagonized multiple oncogenes in colorectal cancer progression." (PMID 32195190, 2020). "The region of gain of chromosome 1p included the colorectal cancer-associated genes REG4 and NOTCH2 and gain of 15q included the genes MAP2K1, SMAD3, SMAD6, and IGF1R, among others." (PMID 31620944, 2019). "As expected, Smad3 significantly enhanced glucose uptake and lactate production in transfected HT-29 colorectal cancer cells that overexpressed miR-1 mimics." (PMID 28471448, 2017). "Taken together, these results are consistent with regulation of cell proliferation and glycolysis in colorectal cancer cells by a cascade controlled by the miR-1/Smad3/HIF-1α axis." (PMID 28471448, 2017). "Evaluation of the differential expression between carcinoma and normal mucosa showed that SMAD3 rs12708491 and rs2414937, NFκB1 rs230510 and rs3821958, and RUNX3 rs6672420 were associated with several miRNAs for colorectal carcinoma." (PMID 28061442, 2017). "TGF-β/Smad3 signaling was known to be one of the most important signaling pathways in the control of colorectal cancer progression." (PMID 27776350, 2016). "Here, we demonstrated that TGF-β1 elevated the expression of miR-155 in colorectal cancer cells through SMAD3 and SMAD4." (PMID 27626488, 2016). "Colorectal cancer (CRC) [MIM:114500] and Loeys-Dietz syndrome 3 (LDS3) [MIM:613795] are both caused by mutations in SMAD3 [UniProt: P84022]." (PMID 26868667, 2016).